LEP (leptin)
Diseases named in the same sentence as LEP in open-access papers (continued):
Sharing a sentence is not in itself a finding about the gene and the disease.
Insulin resistance (continued). "Additionally, one study of MetR for 14 weeks in leptin‐deficient mice observed significant decreases in fasting insulin and HOMA‐IR, without changes in fasting blood glucose, which suggested that improved insulin resistance due to MetR may be independent of leptin and changes in glucose levels." (PMID 40526038, 2025). "At this time, the maternal brain cannot receive the signal of leptin level increase, and the appetite is out of control, thus leading to insulin resistance and the occurrence of GDM; however, the regulation mechanism of leptin in placenta has not been reported." (PMID 36615730, 2022). "In addition, SLGT2/leptin were over-expressed in PDM with poor glycemic control and insulin resistance (never-metformin users vs. metformin-users)." (PMID 34440108, 2021). "Since the serum levels of insulin, leptin and adiponectin were not routinely measured in AHF patients, we could not clarify the relationship between glycemic gap and insulin resistance." (PMID 31000758, 2019). "Our multiple linear-regression model analyzing fasting glucose levels against 10- and 12-Z,E-HODE/LA, insulin and leptin/adiponectin or against insulin and leptin/adiponectin predicted IGT and insulin resistance without the OGTT, with specificity and sensitivity >98%." (PMID 29610560, 2018). "Finally, insulin resistance marker, HOMA-IR, revealed a positive correlation with leptin and a negative correlation with adiponectin level, although the latter disappeared in multiple regression analysis." (PMID 25129652, 2015). "Patients with disease had higher leptin levels and LAR than controls after adjusting for BMI and homeostasis model assessment (HOMA) index, suggesting that LAR was a reliable marker of cardiac syndrome X independent of insulin resistance." (PMID 25793395, 2015). "Lipid restriction may also improve Homeostatic Model Assessment- Insulin Resistance (HOMA-IR) scores, and leptin and proinflammatory cytokines levels regardless of body weight." (PMID 26379757, 2015). "Elevated serum leptin in PCOS women could be due to the positive correlation between leptin and BMI and is independent of insulin resistance." (PMID 26180527, 2015). "Notably, in this very young population, leptin, rather than HMW adiponectin, emerges as a sex-independent discrimination marker of adiposity degree, as well as a sex-related predictor of basal insulin resistance." (PMID 21365005, 2011). "Most studies addressing leptin and insulin report that, after adjustment for BMI, leptin levels in PCOS women do not correlate with the chronic insulin levels, while others report that leptin levels in PCOS women did correlate with measures of insulin resistance." (PMID 26124830, 2015). "In line with other reports showing that FF-leptin levels are predictive of fertilization rates, lower than normal FF-leptin levels in NOW-PCOS may explain their lower fertilization rate and this may be related to the level of insulin and/or insulin resistance." (PMID 24895638, 2014).
diabetes (1,000 papers, 2001 to 2026). "In mice carrying the diabetes mutation (leptin-deficient), the manifestation of the diabetic syndrome depends on genetic background." (PMID 41129566, 2025). "Even in type 2 diabetes mellitus patients associated with leptin insensitivity, melanocortin evades the leptin pathway, increases satiety, and prevents the development of type 2 diabetes mellitus." (PMID 41002740, 2025). "Conversely, leptin-deficient states (including fasting as well as most forms of diabetes) are characterized by hyperactive AgRP neurons while POMC neurons are inhibited." (PMID 40371641, 2025). "Leptin, a key adipokine regulating appetite, energy balance, and metabolism, has been implicated in the pathogenesis of diabetes." (PMID 40630340, 2025). "Leptin, a hormone secreted by adipose tissue, is closely associated with diabetes and other metabolic disorders." (PMID 40242450, 2025). "Type 2 diabetes mellitus is strongly associated with elevated levels of IL-6, leptin, CRP, and TNF-α." (PMID 41155523, 2025). "Our study shows that leptin levels are associated with hypertension and, at lower extent, with diabetes, particularly in women, highlighting a potential link between leptin, metabolic comorbidities, and psoriasis, with a more pronounced effect in women." (PMID 40740781, 2025). "In line with our findings that the PRS of diabetes-related traits are significantly associated with BIs, the “leptin-insulin signaling pathway overlap” was also a top-ranked pathway." (PMID 40650217, 2025). "Stratification by menopausal status, parity, HRT use or diabetes status was also performed, and leptin levels remained a significant predictor of EC risk after control for these potential confounding factors." (PMID 40902078, 2025). "Increased ghrelin signaling in STZ-DM rats, combined with decreased circulating insulin and leptin, activates hypothalamic neuropeptide responses underlying increased food intake in diabetes." (PMID 41195415, 2025). "Regular exercise also helps regulate hormone balances closely related to diabetes, such as leptin and adrenaline, further reducing the risk of diabetes." (PMID 41040857, 2025). "The LEP gene is involved in aging-related neuroendocrine systems and has been linked to age-related diseases such as diabetes and atherosclerosis." (PMID 40417629, 2025). "Children of families with familial hypertension or diabetes have a decreased risk of being in the “low leptin/IGF-1/HbA1c” status as compared to the “normal” status." (PMID 39899498, 2025). "Low adiponectin levels have been associated with both microvascular and macrovascular complications of diabetes, while leptin has shown variable associations with coronary heart disease in patients with type 2 diabetes." (PMID 40655403, 2025). "It has been shown that serum leptin levels are significantly elevated in obese diabetic patients and it is believed that elevated serum leptin levels are associated with an increased risk of diabetes." (PMID 38243194, 2024). "Results showed that patients with higher arterial stiffness were elevated leptin levels, which were significantly associated with increased arterial stiffness, independent from confounding factors, such as age, diabetes, and blood pressure." (PMID 39682585, 2024). "Plasma leptin concentrations and adiposity have also been associated with type 2 diabetes mellitus and metabolic syndrome." (PMID 38289144, 2024). "The fifth family had two children diagnosed and treated with leptin in the diabetes clinic and were confirmed to be homozygous for a mutation in AGPAT2 c.158del, causing a change in the protein p.(Gly53Alafs*8), NM_006412.4." (PMID 38231342, 2024). "Maternal weight also displayed a positive correlation with milk leptin levels, and maternal diabetes status was positively associated with milk insulin concentrations." (PMID 39021603, 2024).
diabetes (continued). "An increased risk of developing diabetes is also associated with increased leptin secretion, resistin and decreased adiponectin secretion by adipose tissue." (PMID 39457712, 2024). "Logistic regression models, adjusting for age, sex, BMI, smoking status, and diabetes duration, were applied to evaluate the associations between adiponectin and leptin levels and DPN risk." (PMID 39735639, 2024). "Higher concentrations of NAC did not have a beneficial effect on the wound healing process in the leptin-deficient murine model of type 2 diabetes mellitus." (PMID 39337474, 2024). "Deficiency in leptin, a fundamental hormone in energy homeostasis, and ectopic fat accumulation can lead to severe insulin resistance, difficult-to-treat diabetes, and hypertriglyceridemia." (PMID 38183080, 2024). "It is known that low leptin levels and poor diabetes control are associated with symptoms of depression." (PMID 38183080, 2024). "Due to its involvement in glucose metabolism and energy expenditure, deficiency of leptin or its resistance causes morbid obesity and diabetes." (PMID 39490585, 2024). "We specifically examined to what extent leptin and adiponectin, as well as hypertension and diabetes, play a mediating role in these associations." (PMID 38627329, 2024). "Increased leptin levels also occur in the amniotic fluid, where an increase of 1 ng/ml in amniotic leptin levels increases the risk of developing diabetes by 4%." (PMID 37964253, 2023). "It is reported that phytate improves lipid and carbohydrate metabolism, increases adiponectin, decreases leptin and reduces protein glycation, which is linked with macrovascular and microvascular diabetes complications." (PMID 36671007, 2023). "Long-term changes in circulating leptin concentrations, either by excess or by deficiency, cause a series of disorders entangled in the pathogenesis of metabolic syndrome, diabetes mellitus, and cancer, among others." (PMID 36674935, 2023). "Leptin is associated with incident diabetes and adverse cardiovascular outcomes, and our aim was to investigate the association of living altitude with serum leptin concentrations." (PMID 36909317, 2023). "Further extensive cohort studies are needed to confirm the roles of adipokines in diabetes-related cognitive impairment pathogenesis and investigate the potential of adiponectin and leptin as diagnostic markers of cognitive dysfunction." (PMID 35682821, 2022). "Leptin is a vital hormone derived from adipose tissue that has been observed to play a significant role in various pathways prompting the risk of diabetes." (PMID 35078449, 2022). "We also found that Igf2bp2 trends lower in adipocytes of leptin-deficient (ob/ob) and leptin receptor-deficient (db/db) obese mice, which model diabetes onset and progression." (PMID 35036870, 2022). "In general, analysis of the association between leptin and novel subgroups of diabetes is valuable for leptin’s clinical applications." (PMID 34996484, 2022). "Fast‐fibre specific atrophy is atypical of disuse models (e.g. immobilization, denervation), but frequently found in conjunction with metabolic disturbance (e.g. diabetes, ageing) where leptin resistance has been implicated." (PMID 35844058, 2022). "Leptin, a neurotrophic hormone, was increased primarily in association with birth weight and secondarily by maternal obesity and diabetes." (PMID 35197933, 2022). "Genetic deletion of PRMT2 has been associated with a lean, leptin-hypersensitive “anti-diabetes-like” phenotype in mice." (PMID 36585686, 2022). "Due to spontaneous deficiency in leptin, ob/ob mice are one of the most commonly used experimental animal models in diabetes research." (PMID 36230421, 2022). "Despite the known role of leptin in coordinating the fibroblastic and inflammatory processes, the major mechanism underlying SS, as well as the diabetes-leptin/diabetes-SS linkages, the role of leptin in the pathogenesis of SS is not clear at present." (PMID 36295022, 2022).
diabetes (continued). "Ob/ob mice, due to spontaneous deficiency in the leptin, are one of the most commonly used experimental animal models in diabetes research." (PMID 36230421, 2022). "In contrast, multiple factors were associated with leptin and insulin, including maternal diabetes, maternal BMI and infant’s birth weight." (PMID 35197933, 2022). "In the same study, BMI and diabetes appeared to affect the association between leptin levels and endometrial cancer risk." (PMID 35053431, 2022). "On the other hand, leptin overproduction by the placenta is associated with diabetes mellitus, hypertension, high BMI, and weight gain during pregnancy." (PMID 35510203, 2022). "The risk increase of diabetes development is also associated with the increased release of a leptin, resistance, and decreased release of adiponectin by fat tissue." (PMID 35054072, 2022). "Most of them found a positive association between leptin and AS both in patients with cardiovascular risk (e.g., chronic kidney disease, coronary heart disease, diabetes, hypertension) and in the general population." (PMID 34385686, 2021). "Umbilical cord leptin levels were associated with pre-pregnancy overweight [coefficient = 1.297, 95% confidence interval (CI) 1.081–1.556, p = 0.005] and diabetes mellitus (coefficient = 1.574, 95% CI 1.206–2.055, p = 0.001)." (PMID 35185642, 2021). "Diabetic biomarker panel profiling revealed substantially higher levels of proteins linked to diabetes including C-peptide, insulin and leptin in the peripheral circulation of the sampled urban population." (PMID 34361920, 2021). "The majority of studies detected a positive association between leptin and AS, including in patients with chronic kidney disease, diabetes, coronary heart disease, or hypertension." (PMID 34385686, 2021). "Surprisingly,leptin significantly reduced blood glucose in mouse models of insulin-deficient diabetes, suggesting that leptin modulated glucose homeostasis independently of insulin." (PMID 34446063, 2021). "In population studies, high leptin levels were associated with the development of diabetes, with differences by sex." (PMID 32131811, 2020). "A number of studies have explored the association between depression and ghrelin, leptin, and cortisol; further, postprandial C-peptide levels have a therapeutic effect on type 2 diabetes mellitus (T2DM)." (PMID 33023555, 2020). "In the Sandy Lake Health and Diabetes Project cohort, the association between high leptin at baseline with an increased risk of incident type 2 diabetes disappeared after adjustment for either waist circumference or BMI." (PMID 32131811, 2020). "It is assumed that lack of leptin signaling and extensive diabetes-caused metabolic disturbances (inflammation, lipid and glucose metabolism) lead to IVD degeneration." (PMID 33396484, 2020). "Our investigation among African Americans in the Jackson Heart Study revealed an association between both leptin and adiponectin and incident type 2 diabetes mellitus." (PMID 32131811, 2020). "The hepatic fibrosis grade rapidly progressed in the cranial surgery cases of NAFLD patients with hypopituitarism, possibly in association with BMI, diabetes mellitus, and leptin." (PMID 33102399, 2020). "Diabetes causes weight loss of body and reproductive organs due to decreased circulating leptin concentration and inducing oxidative stress and testicular atrophy, respectively." (PMID 32607132, 2020). "Diabetes leads to weight loss and increased food intake due to reduced concentration of serum leptin." (PMID 32509880, 2020). "The largest module was enriched with pathways related to leptin, which has been linked to diabetes before, as well as some IGF (Insulin Like Growth Factor) related pathways." (PMID 32735660, 2020). "In congenitally leptin-deficient ob/ob mice, which have severe diabetes and metabolic dysfunction, adiponectin overexpression was able to reverse their phenotype, restoring normal glucose and insulin levels." (PMID 33133017, 2020).
diabetes (continued). "In this study, we aimed to analyze the expression of glycan-processing genes in DRG neurons from a leptin-deficient genetic mouse model of diabetes (db/db)." (PMID 32233724, 2020). "ZDF rats carry the same defect in leptin signaling as Zucker fatty rats and also have a genetic predisposition to diabetes." (PMID 32326226, 2020). "This notion is further exemplified by the observation that pharmacological blockade of T-type channels alleviates diabetes-induced hyperalgesia in a leptin-deficient genetic mouse model of diabetes (ob/ob)." (PMID 32233724, 2020). "Although leptin levels are closely associated with adiposity and increased MetS components, the role of leptin levels in diabetes and prediabetes groups is rather controversial." (PMID 33076921, 2020). "The aim of this study was to explore the association between depression and ghrelin, leptin, cortisol, and C-peptide in patients with diabetes." (PMID 33023555, 2020). "The CPP extract has also ameliorated diabetes-induced pancreatic β cells loss by repairing the antioxidant defense mechanism and restoring insulin, amylin, leptin, and carbohydrate-metabolizing enzyme levels." (PMID 32256963, 2020). "Cord leptin levels can be linked with birth weight of neonates from women with gestational obesity and/or diabetes mellitus as well." (PMID 33114326, 2020). "The prevalence of autoimmune diseases, such as systemic lupus erythematosus (SLE), rheumatoid arthritis (RA), multiple sclerosis (MS) and type 1 diabetes mellitus (T1D), is increasing in affluent countries and associates with serum leptin levels." (PMID 32824322, 2020). "Our previous studies demonstrated that VDAC1 is upregulated and participates in diabetes-related dysfunction in the leptin-deficient db/db mouse model of T2D." (PMID 32093016, 2020). "The differences we found in adipokines levels suggest that in ESRD patients under chronic dialysis, diabetes and higher BMI associate with lower adiponectin and with an enhancement in leptin levels." (PMID 30911344, 2019). "We propose that these markers should be used in combination with adiponectin, leptin, and insulin for the early detection of the risk of diabetes." (PMID 31379415, 2019). "Lipodystrophy syndromes are rare heterogeneous disorders characterized by deficiency of adipose tissue, usually a decrease in leptin levels and, frequently, severe metabolic abnormalities including diabetes mellitus and dyslipidemia." (PMID 29704234, 2019). "In the present study leptin level were significantly lower in CAD patients but increased when diabetes is associated with CAD." (PMID 30674322, 2019). "Celastrol treatment reduces body weight gain and food intake in both high fat-fed obese in diabetes (db/db) and leptin-deficient (ob/ob) mice by potentiating STAT3-dependent leptin signaling and inhibiting ER stress." (PMID 29491837, 2018). "A low-iron diet or iron chelation therapy improves glycemia in diabetes-prone, leptin-deficient mice." (PMID 30454649, 2018). "There is strong evidence that maternal obesity and diabetes are associated with higher cord-blood insulin and leptin concentrations." (PMID 29925339, 2018). "Blood deoxysphingolipid levels are also elevated in animal models of diabetes, for example in the streptozotocin-induced rat diabetes model and in the leptin-deficient ob/ob mouse." (PMID 29778900, 2018). "Leptin-deficient ob/ob mice—the mouse model for obesity-related diabetes—with miR-375 knocked out also experience a reduction in β cell mass that leads to diabetes." (PMID 29770126, 2018). "Homozygote db mice are marked by total leptin resistance due to a receptor mutation and thus develop obesity and diabetes (“diabesity”)." (PMID 28542222, 2017). "Many studies were conducted to investigate the association between leptin and diabetes and their results were contradicted." (PMID 28127544, 2017).